EPRS1 (glutamyl-prolyl-tRNA synthetase 1)
Diseases named in the same sentence as EPRS1 in open-access papers:
EPRS1 is named in the same sentence as 58 diseases in open-access papers, as found by Europe PMC text mining. Sharing a sentence is not in itself a finding about the gene and the disease. The quoted sentences say what the papers report.
hypomyelinating leukodystrophy (9 papers, 2019 to 2025). "EPRS1 is associated with hypomyelinated leukodystrophy and psychomotor developmental delay, epilepsy, and deafness." (PMID 41488750, 2025). "Pathogenic variants of genes encoding aminoacyl-tRNA synthetases (ARS) have been linked to a number of neurodegenerative diseases, including hypomyelinating leukodystrophies (e.g., EPRS1, VARS1, DARS1 and RARS1)." (PMID 39062571, 2024). "Bi‐allelic point mutations in EPRS1 have been discovered in patients with hypomyelinating leukodystrophy, diabetes and bone diseases." (PMID 36411955, 2023). "Variants of the dual‐functional cytoplasmic human glutamyl‐prolyl‐tRNA synthetase, EPRS1, have been associated with leukodystrophy, diabetes and bone disease." (PMID 36411955, 2023). "Several mutations in the PRS portion of human EPRS1 gene were linked with hypomyelinating leukodystrophy, and steady-state aminoacylation assays using patient-derived lymphoblast lysate suggested reduced PRS activity compared with wild-type (WT)." (PMID 34537243, 2021). "Here the authors show that a homozygous EPRS1 missense variant causing hypomyelinating leukodystrophy-15 alters the accessibility of variant-distal methylation sites in EPRS1 mRNA, revealing a new RNA-dependent mechanism by which genetic variants can influence gene expression and disease." (PMID 38769304, 2024). "In the last few years, our group has identified and validated eight genes causative for leukodystrophy, including POLR3A, POLR3B, POLR1C, POLR3D, EPRS1, VARS1, and ABHD16A." (PMID 39062571, 2024). "Hypoactive mutations in the PRS (prolyl-tRNA synthetase) domain of EPRS1 lead to hypomyelinating leukodystrophy without causing cardiac dysfunction in patients, implying that reduced PRS enzymatic activity does not adversely affect the heart." (PMID 40869184, 2025).
breast carcinoma (7 papers, 2015 to 2025). "Furthermore, EPRS1 is upregulated in breast cancer, and its overexpression is linked to an unfavorable clinical outcome." (PMID 37779151, 2023). "In ER+ breast cancer, high expression of EPRS1 predicted shorter overall survival." (PMID 37138286, 2023). "Similarly, data from TCGA and METABRIC cohorts showed that EPRS1 was expressed at high levels in estrogen receptor-positive (ER+) breast cancer tissues and was related to reduced overall survival." (PMID 37779151, 2023). "Moreover, a recent study showed that AKT activation induces nuclear localization of glutamyl-prolyl-tRNA synthetase (EPRS1), which binds to PARP1 and activates PARylation, thereby contributing to breast cancer cell survival." (PMID 40134437, 2025).
viral infection (5 papers, 2019 to 2024). "Viral titers in the brain and spleen of Eprs1+/− mice were higher than those in WT mice, which accounted for the increased susceptibility of EPRS1-deficient mice to viral infection." (PMID 37779151, 2023). "Taken together, these data suggest that EPRS1 triggers intracellular innate immune responses against viral infection." (PMID 37779151, 2023). "Through proteomic analysis, virus infection-specific phosphorylation of EPRS1 at Ser990 but not at Ser999 was identified." (PMID 37779151, 2023).
diabetes (4 papers, 2019 to 2023). "In this study, we report compound heterozygous mutations in EPRS1, which lead to amino acid substitutions P14R and E205G in two patients with diabetes and bone diseases." (PMID 34537243, 2021).
breast tumors (3 papers, 2016 to 2025). "Also identified gains in the copy number of EPRS1 in lung, esophageal, hepatocellular, skin, and breast tumors." (PMID 40818124, 2025).
colitis (2 papers, 2022 to 2023). Inflammation of the colon. "Moreover, in EPRS1-deficient colitis mice, body weight loss, disease activity scores, and damage scores were higher than they were in wild-type (WT) colitis model mice." (PMID 37779151, 2023). "The results showed that EPRS1 whole-body knockdown (Eprs1+/−) mice were more sensitive to DSS-induced colitis than WT mice." (PMID 36309524, 2022).
deafness (2 papers, 2023 to 2025). An inherited or acquired condition characterized by the complete loss of the ability to hear from one or both ears. "We report compound heterozygous variants in a bifunctional aminoacyl‐tRNA synthetase, EPRS1, in a 4‐year‐old female patient presenting with psychomotor developmental delay, seizures and deafness." (PMID 36411955, 2023). "Here, we report compound heterozygous variants in EPRS1 in a 4‐year‐old female patient presenting with psychomotor developmental delay, seizures and deafness." (PMID 36411955, 2023). "In this study, we report novel compound heterozygous point mutations in the ERS region of the EPRS1 gene of a 4‐year‐old patient with psychomotor retardation, epilepsy, and deafness." (PMID 36411955, 2023).
fibrosis (2 papers, 2023 to 2024). the formation of excess fibrous connective tissue in an organ or tissue in a reparative or reactive process. "The EPRS1-positive area was positively correlated with fibrosis, proteinuria, BUN levels, and Col1a1 mRNA levels and negatively correlated with creatinine clearance." (PMID 39623092, 2024).
gastric cancer (2 papers, 2023 to 2025). A primary or metastatic malignant neoplasm involving the stomach. "Considering this, EPRS1 may serve as a potential treatment target, its overexpression predicts poor prognosis in gastric cancer patients." (PMID 40818124, 2025). "Moreover, EPRS1 was also described as a marker for gastric cancer presenting with a greater cell proliferation and tumor growth phenotype." (PMID 37138286, 2023).
hepatocellular carcinoma (2 papers, 2016 to 2023). A malignant tumor that arises from hepatocytes. "In this study, we investigated the carcinogenic function, potential mechanism, and clinical significance of EPRS1 in human hepatocellular carcinoma (HCC)." (PMID 37138286, 2023).
liver cancer (2 papers, 2023 to 2025). An epithelial or non-epithelial malignant neoplasm that arises from the liver. "Recent studies have suggested that EPRS1 may play possible roles in the progression of liver cancer, as it promotes the synthesis of gene sets associated with metastasis (hallmark epithelial-mesenchymal transition)." (PMID 40818124, 2025). "Using the TCGA-LIHC dataset, we discovered considerable duplication of the EPRS1 region in liver cancer tissues, suggesting the mechanism of EPRS1 upregulation in liver cancer." (PMID 37138286, 2023). "Data from bioinformatics analyses, HCC cells, and clinical specimens were combined to describe the novel mechanisms by which glutamyl-prolyl-tRNA synthetase 1 (EPRS1) promotes the synthesis of several downstream proteins and the progression of liver cancer." (PMID 37138286, 2023). "Our results showed that EPRS1 expression was upregulated at both the mRNA and protein levels in liver cancer." (PMID 37138286, 2023). "To confirm the clinical significance of elevated EPRS1 expression in liver cancer, we examined the protein levels of EPRS1 on a tissue microarray using immunohistochemical staining." (PMID 37138286, 2023). "Gene set enrichment analysis was performed to further validate the possible roles of EPRS1 in the progress of liver cancer." (PMID 37138286, 2023). "In conclusion, our study highlights that the CNV of EPRS1 increased EPRS1 expression, which promoted protein synthesis of downstream oncogenic genes and promoted liver cancer progression." (PMID 37138286, 2023). "To figure out whether the high expression of EPRS1 in liver cancer is related to CNV, we used the cBioPortal online tool and found that EPRS1 has obvious CNV in HCC and other tumors." (PMID 37138286, 2023). "EPRS1 was frequently upregulated at the mRNA and protein levels in liver cancer." (PMID 37138286, 2023). "In addition, copy number variation could contribute to the high expression of EPRS1 in liver cancer." (PMID 37138286, 2023).
chronic kidney disease (1 paper, 2024). Impairment of the renal function secondary to chronic kidney damage persisting for three or more months. "Future research may explore EPRS1 inhibitors as potential therapies for chronic kidney disease." (PMID 39623092, 2024). "Therefore, targeting EPRS1 could be a potential therapeutic target for alleviating fibrotic injury in chronic kidney disease." (PMID 39623092, 2024).
glioblastoma (1 paper, 2023). The most malignant astrocytic tumor (WHO grade IV). "The PCG-lncRNA signature, which included EPRS1, could be used to separate patients with glioblastoma into two groups with dramatically differing survival rates (i.e., high- and low-risk groups)." (PMID 37138286, 2023).
glioma (1 paper, 2024). A benign or malignant brain and spinal cord tumor that arises from glial cells (astrocytes, oligodendrocytes, ependymal cells). "In addition to defective m6A modification of mutant EPRS1 mRNA in patient-derived LCLs, defective m6A modification was observed in mutation-bearing reporters in embryonic kidney-derived HEK293T cells and glioma-derived U87-MG cells." (PMID 38769304, 2024).
heart failure (1 paper, 2023). Inability of the heart to pump blood at an adequate rate to meet tissue metabolic requirements. "On the other hand, we cannot rule out the possibility of a secondary effect downstream of heart failure caused by the loss-of-function of Eprs1 as fatty acid oxidation is often compromised and related metabolic enzyme expression is reduced in hypertensive cardiomyopathy and ischemic heart failure." (PMID 38201239, 2023). "In this study, our findings demonstrate that the haploinsufficiency of EPRS1 (heterozygous cKO) in cardiomyocytes does not cause apparent cardiac disorders, while the complete depletion of EPRS1 (homozygous cKO in CMs) leads to severe dilated cardiomyopathy, heart failure, and lethality in the mice." (PMID 38201239, 2023). "Together, these events perturb the proteomic homeostasis in Eprs1 cKO hearts, which may contribute to the progression of heart failure in mice." (PMID 38201239, 2023). "This may indicate a wide safety dose window for using EPRS1 inhibitors for treating heart failure with limited cardiotoxicity." (PMID 38201239, 2023). "Here, we found that heterozygous Eprs1 knockout in CMs does not cause any significant changes in CM hypertrophy induced by pressure overload, while homozygous knockout leads to dilated cardiomyopathy, heart failure, and lethality at around 1 month after Eprs1 deletion." (PMID 38201239, 2023).
heart hypertrophy (1 paper, 2024). "Additionally, Eprs1 haploinsufficiency was shown to reduce heart hypertrophy." (PMID 39623092, 2024).
Hyperglycemia (1 paper, 2023). An increased concentration of glucose in the blood. "Previous studies reported a noncanonical function of phosphor-EPRS1 in activating long-chain fatty acid uptake by binding to SLC27A1 (fatty acid transport protein 1, FATP1) under hyperglycemia stress." (PMID 38201239, 2023).
oral cancer (1 paper, 2025). "The gene EPRS1 (Glutamyl-prolyl-tRNA synthetase 1) is considered the most relevant in our study as it is found to be overexpressed in all samples associated with oral cancer, oral submucous fibrosis, and oral leukoplakia." (PMID 40818124, 2025). "In the survival analysis of these genes in the 522 oral cancer samples, we observed similar trends across all cases, with statistically significant results (p ≤ 0.05) for most markers, except for two of them (EPRS1 and SH3D21)." (PMID 40818124, 2025). "Moreover, the gene EPRS1 was the only one overexpressed in all studied diseases, emerging as a candidate for a potential early biomarker for oral cancer detection." (PMID 40818124, 2025).
oral squamous cell carcinoma (1 paper, 2025). "In oral squamous cell carcinoma (OSCC), suppression of EPRS1 expression in tumor cells has been shown to decrease cell proliferation, indicating a potential functional role for EPRS1 in OSCC development." (PMID 40818124, 2025).
parasite infection (1 paper, 2023). "Halofuginone and other EPRS1-inhibitors have been tested in animals and humans for treating organ fibrosis, parasite infection, and cancer, among other diseases." (PMID 38201239, 2023).
renal fibrosis (1 paper, 2025). A final common manifestation of a wide variety of chronic kidney diseases characterized by glomerulosclerosis and tubulointerstitial fibrosis. "EPRS1 activation has been implicated in renal fibrosis by promoting fibroblast activation and mitochondrial dysfunction, which in turn drive extracellular matrix accumulation and contribute to disease progression." (PMID 40818124, 2025).
tubulointerstitial nephritis (1 paper, 2024). "In tubulointerstitial nephritis, Eprs1 expression is increased in NK cells and γδ T cells in the early phase, and these cells are involved in the immune response." (PMID 39623092, 2024).
ulcerative colitis (1 paper, 2022). An inflammatory bowel disease involving the mucosal surface of the large intestine and rectum. "EPRS1-deficient macrophages do not assemble the early endosomal complex and consequently exacerbate inflammation, decreasing the survival of EPRS1-deficient mice undergoing septic shock and ulcerative colitis." (PMID 36309524, 2022).
cancer (13 papers, 2015 to 2025). A tumor composed of atypical neoplastic, often pleomorphic cells that invade other tissues. "First, the upregulated expression of EPRS1 may be a diagnostic and prognostic (poor) biomarker for multiple cancer types, especially breast cancer." (PMID 37779151, 2023). "In conclusion, based on its multiple noncanonical functions in a stress- and interactor-specific manner, EPRS1 shows great therapeutic and diagnostic potential in the context of many disorders, including infection, inflammation, metabolism-related immune dysregulation, and cancer." (PMID 37779151, 2023). "The unique gene that was found in all cancer and oral potentially malignant disorders was EPRS (glutamyl-prolyl-tRNA synthetase 1), with a fold change of 0.653 (C vs N), 0.492 (F vs N) and 0.091 (L vs N) (Supplement 4)." (PMID 40818124, 2025). "EPRS1, methionyl-tRNA synthetase 1 and lysyl-tRNA synthetase 1 also play essential roles in the progression and metastasis of cancer cells by regulating different signals." (PMID 36675119, 2023). "Collectively, these results suggest that EPRS1 is a critical regulator of cell proliferation, estrogen signaling, and the development of specific cancers." (PMID 37779151, 2023). "Glutamyl-prolyl-tRNA synthetase 1 (EPRS1) is an aminoacyl-tRNA synthase involved in the pathology of cancer and other diseases." (PMID 37138286, 2023). "Modulation of the EPRS1 interaction via its binding proteins may be another effective therapeutic strategy for preventing cancer development." (PMID 37779151, 2023). "The sensory function of EPRS1 is overly activated to maintain cancer cell survival." (PMID 37258576, 2023). "In addition, by analyzing the expression of EPRS1 in all the cancer types from the TCGA database, we found that EPRS1 is highly expressed in a variety of other tumors." (PMID 37138286, 2023). "The involvement of EPRS1 in diseases such as cancer is also discussed." (PMID 37779151, 2023). "In addition to direct EPRS1 inhibitors, investigation into potential antagonists that block EPRS1 phosphorylation and dissociation from MSCs (e.g., kinase inhibitors) are interesting candidates for application to cancer therapy." (PMID 37779151, 2023). "In addition, we found that inhibition of EPRS1 effectively decreased cancer cell proliferation and migration, whereas enforced EPRS1 expression promoted malignancy, indicating that EPRS1 might contribute to tumor development." (PMID 37138286, 2023). "Therefore, halofuginone may be used to inhibit inflammatory responses and cancer progression because it suppresses EPRS1 activity." (PMID 37779151, 2023). "EPRS1 could promote cancer cell proliferation, characteristics of cell stemness, and mobility." (PMID 37138286, 2023). "Hence, the EPRS1-Dus2 interaction might effectively drive the proliferation of cancer cells, possibly by promoting tRNA charging activity." (PMID 37779151, 2023). "Specific aaRSs that are differentially upregulated across many cancer types include TARS1 (n = 23), DARS2 (n = 22), GARS1 (n = 21), YARS2 (n = 21), EPRS1 (n = 20), AIMP2 (n = 19), and FARSA (n = 18)." (PMID 33266490, 2020).
tumor (10 papers, 2016 to 2025). "Together, our data imply that enhanced EPRS1 contributes to the development of HCC by increasing the expression of oncogenes in the tumor microenvironment." (PMID 37138286, 2023). "The results indicated the differential expression of EPRS1 was most obvious in the tumor samples compared with normal tissues." (PMID 37138286, 2023). "The results revealed stronger EPRS1 staining in tumor regions than their matched non-tumor tissues." (PMID 37138286, 2023).
infection (7 papers, 2012 to 2025). The state of being infected such as from the introduction of a foreign agent such as serum, vaccine, antigenic substance or organism. "While EPRS1 integrates signals from multiple stimuli such as infection, inflammation, and metabolic disorders, there are apparent differences in the kinetics of EPRS1 phosphorylation and physiological function." (PMID 36309524, 2022). "Together, these observations provide a mechanistic rationale that reduced EPRS1 at late infection could dampen GAIT-mediated anti-inflammatory control, contributing to excess cytokine output and tissue damage in ASFV pathogenesis." (PMID 41465783, 2025). "Thus, decreased EPRS1 expression may contribute to uncontrolled cytokine signaling and tissue injury during late infection." (PMID 41465783, 2025).
metabolic disease (2 papers, 2022 to 2023). A congenital disorder (due to inherited enzyme abnormality) or acquired (due to failure of a metabolically important organ) disorder resulting from an abnormal metabolic process. "In addition, many questions must be answered to determine the mechanism through which the metabolic disease of S6K1-deficient mice was attenuated by the introduction of a single EPRS1 S999D protein, as S6K1 likely regulates multiple downstream targets." (PMID 37779151, 2023).
heart disease (1 paper, 2023). "Cardiac dysfunction and heart disease were not reported in these patients, indicating that the mild or moderate loss of function of EPRS1 protein may not cause detrimental effects on the heart." (PMID 38201239, 2023).
neurological disease (1 paper, 2023). "The neurological disease‐associated EPRS1 mutations moderately disrupt tRNAGlu binding and the subtle conformational differences observed, especially for the I212T variant, likely contribute to reduced tRNA affinity and aminoacylation activity." (PMID 36411955, 2023).
EPRS1 also shares sentences with these, for which no sentence is quoted: epilepsy (2 papers); psychomotor developmental delay (2); Q fever (2); type 2 diabetes (2); adenocarcinoma (1); Alzheimer disease (1); anemia (1); bacterial infection (1); chordoma (1); colon adenocarcinoma (1); COVID-19 (1); endocarditis (1); focal segmental glomerulosclerosis (1); HIV-1 infection (1); Leigh syndrome (1); lung adenocarcinoma (1); malaria (1); melanoma (1); microcephaly (1); neurodevelopmental disorder (1); Obesity (1); Oral leukoplakia (1); oral submucous fibrosis (1); Parkinson disease (1); prostate carcinoma (1); proteinopathies (1); psychiatric diseases (1); Sepsis (1); septic shock (1).